SMAD4 (SMAD family member 4)
Diseases named in the same sentence as SMAD4 in open-access papers (continued):
Sharing a sentence is not in itself a finding about the gene and the disease.
colon carcinoma (continued). "With the impact of SMAD4/Tgfβ pathway on cancer invasion, it raises the question of how SMAD4 directly impacts cancer invasion, particularly in colon cancers." (PMID 38136364, 2023). "In this study, we apply deep learning to digitized pathology images to explore compartment level expression and prognostic impact of IRS-1, IRS-2, RUNX3, and SMAD4 in resected tumors from 452 colon cancer patients." (PMID 36900240, 2023). "We confirm previous studies reporting preserved RUNX3 and SMAD4 in the tumor epithelial compartment as positive prognosticators in colon cancer." (PMID 36900240, 2023). "High expression levels of IRS1, RUNX3, and SMAD4 are positive prognostic factors in stage I–III colon cancer." (PMID 36900240, 2023). "The models provide a valuable system to study and assess the critical and complex role of SMAD4 in colon cancer invasion." (PMID 38136364, 2023). "Recently, scientists found that certain miRNA directly regulates Smad4 expression in cancer aggression, and miR-20a-5p negatively regulates Smad4 in colon cancer by specifically targeting it's 3' UTR." (PMID 36807774, 2023). "In this study, we explore the expression and prognostic impact of IRS-1, IRS-2, RUNx3, and SMAD4 in colon cancer." (PMID 36900240, 2023). "A previous study demonstrated that SMAD4 inhibited tumor metastasis in patients with colon cancer through multiple processes including the inhibition of apoptosis, epithelial–mesenchymal transition (EMT), and the PI3K/AKT signaling pathway." (PMID 36127339, 2022). "Studies have found that miR-19b-3p is involved in colon cancer proliferation and drug resistance by targeting mothers against decapentaplegic homolog 4 (SMAD4)." (PMID 35067169, 2022). "CNVs specific for MSS colon cancer IntOMICS identified edges from CNV to associated GE in five out of six genes of interest: KRAS, MYC, BIRC5, RAC3, and SMAD4." (PMID 35996085, 2022). "Such combination of analyzing the TSR and staining for another transcription factor (SMAD4) improved prediction of clinical outcome in colon carcinoma." (PMID 34834440, 2021). "BRAF mutation, SMAD4 loss, and KRAS mutation are all associated with inferior survival among patients with colon cancer." (PMID 33874958, 2021). "The authors demonstrated that genetic depletion of SMAD4 in colon cancer cells allows TGF-β-induced proliferation, migration, and invasion, whereas its ectopic re-expression reverts the tumorigenic effects induced by TGF-β." (PMID 34439114, 2021). "Loss of SMAD4 has also been shown to induce alternative ERK pathways to induce migration and invasion of colon cancer cells in vitro, to enhance liver metastasis in vivo, and to shorten the survival of metastatic tumor-bearing mice." (PMID 34439114, 2021). "The previous report shows that SRI has a possible prognostic value in childhood lymphoblastic leukemia, while inactivation of Smad4 results in drug resistance in colon cancer." (PMID 34163033, 2021). "Correlating with our data, Act-A triggered p21-dependent cell cycle arrest and apoptosis in Smad4-intact colon cancer cells, whereas the deletion of Smad4 gene attenuated the protein anti-cancer activities." (PMID 34867090, 2021). "The Smad4 is attached to the receptor and thus regulated SMADs overwhelm colon cancer cell migration by regulating MMP-9 activity." (PMID 34096454, 2021). "TGF-β pathway undergoes changes in lots of colon cancers mainly through receptor mutation (TGF-βRII) and mutations in components of the intracellular signaling pathway (Smad4)." (PMID 34094025, 2021).
colon carcinoma (continued). "The Smad4-intact SW480 and Smad4-null HT29 colon cancer cell lines were treated with activins and follistatin, and cell cycle was analysed by flow cytometry." (PMID 34867090, 2021). "By suppressing SMAD family member 4 (SMAD4), which has been identified as a common mediator for cell motility promotion, miR-144 impedes cell migration and invasion in colon cancer." (PMID 33046994, 2020). "By controlling the expression of SMAD4, miR-144 inhibits invasion and migration of colon cancer cells." (PMID 32211396, 2020). "It has been shown that TGF-β1 can stimulate VEGF expression in SMAD4-null colon cancer cells by activating the ERK1/2 and p38 MAPK signaling pathways." (PMID 32152452, 2020). "The present study focused on the effect of miR-144 and SMAD4 on colon cancer in order to find the novel gene therapy target for the treatment of colon cancer." (PMID 30745456, 2019). "First, the mRNA and protein levels of SMAD4 were detected by qRT-PCR and Western blotting in human colon cancer tissues." (PMID 30745456, 2019). "SMAD4, mRNA, and protein levels were significantly increased in colon tumor tissues compared with normal colon tissues (P<0.01)." (PMID 30745456, 2019). "In the present study, SMAD4 was considered to be a downstream target of miR-144 in colon cancer progression." (PMID 30745456, 2019). "We found that miR-144 inhibited the proliferation, migration and invasion of human colon cancer cells by targetting SMAD4." (PMID 30745456, 2019). "Smad4 has also been demonstrated to suppress the Wnt/beta-catenin pathway in human colon carcinoma cells and pancreatic ductal adenocarcinoma cells." (PMID 29103082, 2018). "A SMAD4 immunohistochemistry expression study has shown a correlation with poor survival in colon cancer." (PMID 29133385, 2018). "Our results and others suggested pro-tumor function of miR-27 and anti-tumor function of SMAD4 in colon cancer." (PMID 29065177, 2017). "SMAD4 inactivation in colon cancer patients was more likely to be observed in older patients and in those with a later tumor stage." (PMID 28199217, 2017). "To further investigate the effect of SMAD4 in colon cancer lymphangiogenesis, we overexpressed or knocked down SMAD4 in HLECs and monitored tube formation." (PMID 29065177, 2017). "The inverse relationship between miR-19b-3p and SMAD4 in colon cancer cell lines and tumor samples was investigated in our study." (PMID 28938919, 2017). "Further, the actin-binding protein Tagln2 was suggested as a diagnostic biomarker of HCC as it is overexpressed in 69% of patients and was described to be a target of TGF-β/Smad4 in colon cancer cells." (PMID 28994702, 2017). "The roles of miR-19b-3p and its candidate target gene, SMAD4, in colon cancer progression were examined both in vitro and in vivo." (PMID 28938919, 2017). "Results indicated that patients whose localized colon tumors were miR-19b-3p positive presented a significantly lower SMAD4 expression pattern." (PMID 28938919, 2017). "Subsequent western blotting analysis were performed and confirmed that SMAD4 protein levels were significantly overexpressed in transfected miR-19b-3p inhibitor colon cancer cells, consistent with the results of qRT-PCR." (PMID 28938919, 2017). "Colon cancer and adjacent normal sections were stained for SMAD4, TGFβ1, and CD11b, a myeloid lineage marker expressed by tumor-associated macrophages, neutrophils, and other inflammatory cells (N = 19)." (PMID 27270652, 2017). "In this study, we have identified miR-27a as a key regulator of lymphangiogenesis by targeting SMAD4 in colon cancer." (PMID 29065177, 2017). "We have previously reported that activin decreases cell viability in colon cancer cells through a SMAD4-dependent pathway (canonical signaling)." (PMID 28418896, 2017).
colon carcinoma (continued). "We and others have found SMAD-independent signaling is associated with distinct functional effects that occur parallel to SMAD signaling in SMAD4 wild type colon cancer cells." (PMID 26497569, 2015). "A previous study confirmed that the TGFβ/Smad4 pathway has an important role in the chemoresistance of colon cancer cells to Dox-induced cell death." (PMID 25684678, 2015). "Although activin and TGFβ share growth suppressive SMAD signaling in colon cancer, they diverge in their SMAD4-independent pro-migratory signaling utilizing distinct mitogenic signaling pathways that affect EMT." (PMID 26497569, 2015). "Colon cancer cell lines (+/− SMAD4) were interrogated for ligand-induced PI3K and MEK/ERK pathway activation and downstream protein/phospho-isoform expression/association after knockdown and pharmacologic inhibition of pathway members." (PMID 26497569, 2015). "It was interesting to determine that inactivation of Smad4 in patients with colon cancer was more likely to be found in older populations and in patients with a later tumor stage." (PMID 25333693, 2014). "The biological function of miRNA-130a/301a/454 on colon cancer cells is likely mediated by suppression of Smad4, and the up-regulation of the miRNAs is correlated with Smad4 down-regulation in human colon cancers." (PMID 23393589, 2013). "As expected, Pearson correlation coefficient analysis suggested that Smad4 expression was inversely correlated with miR-130a/301a/454 expression in colon cancer tissues." (PMID 23393589, 2013). "Proteomic screen of SMAD4 wt and SMAD4 deficient cell lines detected different protein levels in cell lines pointing to SMAD4 dependent and independent TGF-β responses in colon carcinoma cells." (PMID 22943793, 2012). "TGF-β induced proliferation, migration, invasion, tumorigenicity and metastasis in Smad4-null colon cancer cells, and these TGF-β-induced oncogenic effects were reversed when Smad4 expression was restored." (PMID 22905131, 2012). "The ACVR2/TGFBR2/SMAD4 wild type microsatellite stable colon cancer cell line FET and ACVR2/TGFBR2 wild type/SMAD4-null SW480 colon cancer cells were treated with either activin or TGFβ and cellular growth was assessed." (PMID 22761777, 2012). "To test and compare the effects of activin and TGFβ on cell growth, we used colon cancer cell lines with differing SMAD4 status in addition to SMAD4 knockdown." (PMID 22761777, 2012). "To confirm that the ligand effects on p21 were directly dependent on SMAD4, we knocked down SMAD4 in SMAD4 wild type FET colon cancers cells using siRNA." (PMID 22761777, 2012). "In the current work, we focused on colon carcinoma (SW480) cells to define potential Smad4 target genes involved in the neoplastic transformation process of this particular cell type." (PMID 21492476, 2011). "Smad4 re-expressing SW480 cells served as a model system to investigate the effects of the tumor suppressor Smad4 reconstitution on the nuclear protein composition of human colon carcinoma cells." (PMID 21492476, 2011). "We next sought to analyse laminin expression in Smad4-deficient and Smad4-reexpressing SW480 and SW620 human colon cancer cells in response to TNFα and to the combination of TGFβ and TNFα cytokines." (PMID 20307265, 2010). "Previously, we have established Smad4-positive derivatives from the colon carcinoma cell line SW480 by stable transfection." (PMID 18664273, 2008). "Growth inhibitory effects of TGF-β have been previously reported in SMAD-4 null pancreatic and colon cancer cells." (PMID 18157915, 2007). "This notion is reinforced by previous studies showing that TGF-β upregulates TAGLN2 expression in human adipocytes, promotes Smad4-dependent vascular invasion in hepatocellular carcinoma, and directly activates TAGLN2 transcription via the TGF-β/Smad4 pathway in colon cancer cells." (PMID 41169389, 2025).
colon carcinoma (continued). "For example, TGF-β1 has been shown to impair stem cell activity, cell proliferation, and secretory cell differentiation in Smad4-deficient intestinal organoids, while human IBD (and colon cancer) specimens show reduced Smad4 expression compared to healthy controls." (PMID 41383600, 2025). "In colon cancer, miR‐27a may have an effect on promoting lymphangiogenesis and migration by targeting SMAD4." (PMID 39840720, 2025). "SMAD4 mutations were more frequently associated with colon tumors as opposed to rectal tumors in the EoCRC group, whereas no anatomical preference was observed in the LoCRC group." (PMID 41075061, 2025). "Smad4 expression was down-regulated in UC, CD, and colon cancer tissues." (PMID 39664586, 2024). "Similarly, in colon cancer, cancers that lack SMAD4 expressed more CCL15, which attracted CCR1+ myeloid cells, leading to enhanced liver metastasis." (PMID 38731942, 2024). "However, further studies are needed to draw conclusions on the role of stromal SMAD4 expression in colon cancer." (PMID 36900240, 2023). "In colon cancer, SMAD4 inactivation promotes malignancy and drug resistance." (PMID 38003265, 2023). "Although mutation frequency of SMAD4 is high in pancreatic and colon cancer, there still are no drugs targeting SMAD4." (PMID 36161776, 2023). "Based on weak to moderate correlations with tumor epithelial and stromal RUNX3, IRS-1, CD8+ TIL density, and stromal miR126, stromal SMAD4 expression in colon cancer is likely involved in complex interactions between tumor epithelial cells and different types of stromal cells." (PMID 36900240, 2023). "Examples of such escape include the mutation of SMAD4 in pancreatic ductal adenocarcinoma (PDAC) and gastric cancer (GC), the TβR I mutation in colon cancer, and even mutations in genes that encode TGF-β ligands (BMP5), receptors (TβR II, AVCR2A, BMPR2), and SMADs (SMAD2 and SMAD4)." (PMID 35461253, 2022). "In colon cancer cells, the transcription factors SMAD family member 4 (SMAD4) and specific protein 1 (SP1) activated RHOA expression, while c-Myc was reported to interfere with the binding of SP1 to the RHOA promoter, leading to downregulation of RHOA expression." (PMID 35563826, 2022). "Furthermore, the depletion of SMAD4 expression or the activation of RICTOR/AKT signaling contributed to resistance to irinotecan in colon cancer cells." (PMID 36142267, 2022). "Additionally, the effects of activins and follistatin proteins related to cell cycle and expression of apoptosis markers were investigated in the Smad-4 intact SW480 and Smad-mutated HT29 colon cancer cells." (PMID 34867090, 2021). "Moreover, the restoration of Smad4 suppresses the Wnt/β-catenin signaling activity and ability to migrate in human colon carcinoma cells." (PMID 33322272, 2020). "Promoter binding analysis revealed that Smad4 was associated with KRT23 expression in migratory colon cancer cells, and KRT23 exhibited Smad4-dependent upregulation, thus influencing cell signal transduction and eventually promoting colon cancer cell migration." (PMID 33204716, 2020). "For example, functional enrichment and survival analysis showed that miR-19b-3p might affect the apoptosis and proliferation of human colon cancer cells through SMAD family member 4 (SMAD4) and serve as a prognostic marker for colon cancer." (PMID 32582275, 2020).
colon carcinoma (continued). "APC, SMAD4, NF1 (neurofibromin 1), ARID5B, NCOR1 (nuclear receptor corepressor 1), IGFR1R (insulin like growth factor 1 receptor) and GNAS (GNAS complex locus) were the most often mutated genes in patient-derived colon cancer cells." (PMID 33050525, 2020). "SMAD4 mediates the signaling of transforming growth factor beta and bone morphogenic protein ligands and is a well-defined tumor suppressor in pancreatic and colon cancer." (PMID 33643409, 2020). "In summary, we identified that miR-144 inhibited colon cancer cells proliferation, invasion, and metastasis, which might be by targetting SMAD4." (PMID 30745456, 2019). "Our findings suggested that miR-144 inhibited the onco-process of colon cancer cells through suppressing cell proliferation, migration, and invasion, which might be down-regulated by targetting SMAD4 expression." (PMID 30745456, 2019). "SMAD4 inhibits lymphangiogenesis and migration colon cancer." (PMID 31073530, 2019). "Smad4 has been confirmed to suppress Wnt/beta-catenin signaling activity in colon carcinoma." (PMID 29103082, 2018). "Furthermore, decreased SMAD4 expression, a downstream target of TGF-β, is associated with poor prognosis in colon cancer, providing indirect evidence that inactivation of TGF-β signalling leads to the invasive behaviour of colon cancer." (PMID 29588449, 2018). "Previous study indicated that TGF-beta could affect growth arrest through upregulating p21 in a SMAD4-dependent manner in colon cancer." (PMID 28053288, 2017). "Our findings demonstrate the role of miR-19b-3p-SMAD4 axis in colon cancer progression, which may become a potential therapeutic target against chemotherapy resistance." (PMID 28938919, 2017). "In this study, we demonstrated that SMAD4 is the direct target of miR-19b-3p in colon cancer." (PMID 28938919, 2017). "As PI3K/Akt signaling is a known regulator of p21 in cancer, to elucidate the SMAD4-independent signaling of activin in colon cancer, we hypothesized that the activin receptor directly engages the PI3K/Akt pathway upstream of SMAD4." (PMID 26497569, 2015). "Therefore, we cannot rule out the possibility that these miRNAs also participate in the down-regulation of Smad4 expression in the development of colon cancer." (PMID 23393589, 2013). "To understand the clinical significance of miR-130a/301a/454 and its target in colon cancer, we determined the levels of miR-130a/301a/454 and protein expression of Smad4 in 14 pairs of matched colon cancer specimens by qRT-PCR and immunoblotting, respectively." (PMID 23393589, 2013). "We found that a large subset of colon cancers showed loss of nuclear p21, and that this loss was associated with preservation of ACVR2, suggesting decreased signaling through the SMAD4/p21 axis, but intact activin SMAD4-independent signaling." (PMID 22761777, 2012). "Smad4-reconstituted colon carcinoma cells like adenoma cells respond to TNFα with an increased expression of all three chains encoding laminin-332; coincubation with TGFβ and TNFα leads to synergistic induction and to the secretion of large amounts of the heterotrimer." (PMID 20307265, 2010). "Smad4-reexpressing colon cancer cells displayed similar, although less pronounced effects." (PMID 20307265, 2010). "Furthermore, Tgfβ signaling has also been found to be critical in suppression of BRAF-driven oncogenesis in right-sided colon cancers, suggesting that Smad4/Tgfβ plays a significant role in serrated colon cancer progression, yet there are still substantial gaps in the current knowledge." (PMID 38136364, 2023).